CD44 (CD44 molecule (IN blood group))
Diseases named in the same sentence as CD44 in open-access papers (continued):
Sharing a sentence is not in itself a finding about the gene and the disease.
breast carcinoma (continued). "Several studies have shown that CD44+/CD24- cells increase therapeutic resistance and invasiveness and are correlated with a poor prognosis in breast cancer patients." (PMID 38831317, 2024). "TNBCs, the basal subtype of breast cancer, which is highly metastatic due to the presence of CD24−/CD44+‐breast CSCs, often express epidermal growth factor receptor (EGFR) in high levels, which serve as a biomarker." (PMID 38522013, 2024). "Our data indicated that MDA-MB-231 and Hs-578t cells showed high percentages of CD44+/CD24− cells, in agreement with previous studies reporting 85–99% of CSCs in breast cancer cell lines." (PMID 38392969, 2024). "CD44 and EMMPRIN/CD147 co-operate to transport MCT1 and MCT4 at the plasma membrane in breast cancer cells." (PMID 38796656, 2024). "SMS2 decreased the CD24 transcription level but increased the transcription levels of stemness-related genes including CD44, ALDH, OCT 4 and SOX2 in breast cancer cells." (PMID 38285090, 2024). "In this study, we showed that in two breast cancer cell lines – MDA-MB-231 and MCF-7 – subpopulations with the CD44+/CD24- surface marker phenotype have increased miR-10b expression relative to their parental cell line or other subpopulations." (PMID 39189967, 2024). "In contrast to the results observed in breast cancer cells, prolactin stimulation in the normal mouse mammary epithelial cell line HC11 led to a significant downregulation of CD44." (PMID 39201626, 2024). "Compound 1e potentiated the doxorubicin‐mediated inhibitory effect on proliferation, migration, in‐vitro tumorigenesis capacity, and induction of apoptosis in MDA‐MB‐231 cells, and in the sorted CD24+‐breast cancer cells and CD24−/CD44+‐breast CSC populations." (PMID 38522013, 2024). "Our research outcomes encompass successful multiplexed immunolabelling of Her2, CD44, and EpCAM in the SK-BR-3 and MDA-MB-231 breast cancer cell lines." (PMID 39170968, 2024). "We used mouse mammary carcinoma cells, BJMC3879 Luc2 (Luc2 cells) as the source of CD44-positive EVs and mouse endothelial cells (UV2 cells) as the recipient cells in the niche." (PMID 39273689, 2024). "The other biomarker, CD44, has been discovered to positively modulate the nuclear factor of erythroid-2-like 2 (the main regulator of antioxidant genes) in DOX-resistant breast cancer cells." (PMID 39062149, 2024). "Cell-surface markers like CD44+/CD24− and cytosolic stemness marker ALDH+ are widely used for the enrichment of CSCs from breast cancer." (PMID 39201646, 2024). "Consistently, TNBC is histologically poorly differentiated and displays enhanced stemness compared to other breast cancer subtypes, as evidenced by a higher proportion of CD44+CD24− and ALDH+ breast cancer stem cells (BCSCs)." (PMID 39563370, 2024). "100% tumor incidence was observed in the mice transplanted with CD24+‐breast cancer cells and CD24−/CD44+‐breast CSCs." (PMID 38522013, 2024). "TM-induced ER stress reduces the growth and invasion of CD44+/CD24− cells, indicating TM therapy is an exciting approach to target breast cancer stem cells." (PMID 38474359, 2024). "Breast cancer stem cells (BCSCs) can easily switch between the ME phenotype EpCAM+CD49f+ ALDH1+, and EM phenotypeEpCAM− CD49f+ are positive for CD44/CD24." (PMID 39238997, 2024). "After Musashi knockdown, multiple additional CSC characteristics were downregulated in breast cancer, including the AKT/PI3K pathway, CD133, pERK, tumor spheroid formation, CD44, and HES2." (PMID 37620963, 2023). "In breast cancer, BMP2 can regulate EMT and stemness by upregulating CD44 and MMP11 via PI3K/AKT and Smad signalling pathways." (PMID 37333824, 2023). "Thirdly, current studies usually focus on several aptamers including CD44, CD133, and EpCAM or several cancer types, such as glioma and breast cancer." (PMID 36969696, 2023). "CD44 is a transmembrane glycoprotein and known as a CSC marker in breast cancer and other malignancies." (PMID 37064130, 2023).
breast carcinoma (continued). "Single-chain variable fragments (scFvs) selected from a comprehensive RNA library of lymphocytes from breast cancer patients showed excellent selectivity for CD24 and CD44 when combined with epirubicin." (PMID 37846296, 2023). "Consistent with the prognostic significance of ESRP1 in breast cancer, ESRP1 was demonstrated to promote lung metastasis in orthotopic mouse model of breast cancer by regulating alternative splicing of CD44 mRNA." (PMID 38110955, 2023). "Using the cell surface markers Epithelial Specific Antigen (ESA+), CD44+, and CD24−, populations of stem-cell-like cells in breast cancer can be identified." (PMID 37468874, 2023). "The findings of sustained CD44+ CRC and CD44i35 in a similar quality upon therapy and completion suggest a continued pathological status in post-surgery breast cancer patients." (PMID 36100762, 2023). "The basal-like subtype is a triple-negative aggressive BC with a poor clinical outcome, consisting of a great proportion of breast cancer stem cells and characterized by the most common BCSC biomarkers, CD44+/CD24−/low and ALDH1+." (PMID 37374142, 2023). "Alternative splicing of CD44 under the control of splicing factor ESRP1 has been shown to increase migration and lead to metastasis in breast cancer, ovarian cancer, and melanoma." (PMID 37457440, 2023). "Co-expression analysis using the TCGA database identified a positive relationship between CD44 and MMP-9 in breast cancer." (PMID 37185776, 2023). "High expression of CD44, CD133, ALDH and low expression of CD24 are well-acknowledged biomarkers in maintaining the stemness of CSC in solid tumors, including breast cancer and lung cancer." (PMID 37353799, 2023). "Accordingly, in clinical specimen of breast cancer patients, the specific EMT markers, such as Vimentin, Zeb1, Twist1, β-catenin, and MMP9 showed opposite expression patterns between the CD44+CD24− phenotype and the ALDH+ phenotype." (PMID 36768876, 2023). "The TNBC cells transplanted were CD44+/CD24−, indicating they were prospective breast cancer stem cells." (PMID 36765535, 2023). "CD44 3'-UTR overexpression inhibits tumor proliferation, angiogenesis, and docetaxel resistance in breast cancer by serving as a competitor to the CDC42 3'-UTR for miR-216a, miR-330, and miR-608 binding." (PMID 37771777, 2023). "It is postulated that the group of CD44 and CD24 receptors are favorable prognostic markers in breast cancer." (PMID 38201547, 2023). "The induction of EMT in immortalized, nontumorigenic human mammary epithelial cells resulted in acquisition of the CD44+/CD24– phenotype, a characteristic of breast cancer stem-like cells (CSC)." (PMID 37377604, 2023). "In the breast cancer model, mice were injected into the left and right fat pads with tumor implants containing CD44+CD24– and CD44+CD24+ CSCs, respectively." (PMID 36810098, 2023). "CD44 is a surface marker of CSCs and has been reported to act as a co-receptor for EGFR that activates downstream signaling in breast cancer." (PMID 37924112, 2023). "The surface expression of CD44+ high; CD24− low cells has been considered a stem population marker of breast cancers." (PMID 37507768, 2023). "Low DYRK2 expression upregulates CD44+/CD24− and ALDH1+ CSCs in pulmonary metastases of breast cancer." (PMID 37886981, 2023). "For example, CD44+CD24−/low and ALDH+ CSCs were characterised in breast cancer, along with CD133+CD44+ in colon, brain, and lung cancer; CD34+CD8− in leukaemia; CD44+ in head and neck tumours; CD90+ in liver cancer; and CD44+/CD24+/ESA+ in pancreatic cancer." (PMID 36902427, 2023). "Two types of DNA aptamers were used: one was a CD44 aptamer for targeting CD44+ breast CSCs, and the other was an aptamer for targeting transmembrane glycoprotein mucin 1 (MUC1) expressed on breast cancer cells." (PMID 37720349, 2023). "For example, in MB-231 breast cancer cells grown in culture and in vivo, FM-miR-34a induced stronger silencing of MET and CD44 in comparison to PM-miR-34a." (PMID 37666938, 2023).
breast carcinoma (continued). "DYRK2 expression was inversely correlated with CD44+/CD24− subpopulations and mammosphere formation in breast cancer specimens and cell lines." (PMID 37886981, 2023). "CSCs have been shown to exhibit three interchangeable phenotypes in breast cancer, namely, ALDH+, CD44+CD24−, and ALDH+CD44+CD24− CSCs, which indicates the plasticity and heterogeneity of CSCs." (PMID 36890838, 2023). "In vitro results demonstrated that ASR490 significantly inhibited BCSCs (ALDH+ and CD44+/CD24–) and breast cancer (BC) growth at nM concentrations, and subsequently inhibited the colony- and mammosphere-forming abilities of BCSCs and BCs." (PMID 36909163, 2023). "BCSCs which are CD44+/CD24− and ALDH+ have robust tumor-initiating capacity and are involved with the incidence of chemoresistance and breast cancer relapse." (PMID 38090567, 2023). "This combination, Apt1-Liposome, allowed a better cellular uptake of the conjugated molecule in CD44 positive cell lines A549 (lung cancer) and MDA-MB-231 (breast cancer)." (PMID 35785191, 2022). "Two breast cancer cell lines, i.e., MDA-MB-231 and MCF-7, were chosen, as they showed different expression levels of CD44 mRNA." (PMID 36231028, 2022). "Taken together, these results suggest that CD44 regulates FOXA2 localization through AKT and promotes metastasis in breast cancer cells." (PMID 36289750, 2022). "Our study aimed to understand how CD44 and TrkA interact and the consequences of inhibiting this interaction regarding the pro-tumoral effect of NGF in breast cancer." (PMID 35346305, 2022). "MTT analysis showed the reduced viability of the breast cancer cell line, whereas, FACS study emphasizes that both the CD44 and CD326 populations of the breast cancer cells have been significantly decreased." (PMID 35152903, 2022). "To further validate our results from PyMT tumors, we also utilized a human luminal breast cancer cell line, MCF-7, and its sorted BCSCs, CD24−/CD44+ for determining BGN expression." (PMID 35053617, 2022). "Our current results suggest that the C‐terminus of PTX3 directly interacts with the N‐terminus of CD44, consequently activating metastasis/invasion and stemness through the involved genes by activating the AKT, ERK1/2 and NF‐κB pathways in breast cancer cells." (PMID 35090088, 2022). "The membrane-associated RING-CH (MARCH), transmembrane E3 ligase, is downregulated in breast cancer tissues and interacts with CD44, a glycoprotein target subject to MARCH8-dependent lysosomal degradation in breast cancer." (PMID 36605595, 2022). "The cells were characterized using typical combinations of markers for breast cancer stem cells (CD24−, CD44+, ALDH1+)." (PMID 36077622, 2022). "The putative stem cells CD44+ and CD24-/low can be detectable in the metastatic pleural fluid found in breast cancer and are mainly responsible for generating primary tumors in an orthotopic site and cause lung metastasis." (PMID 35800881, 2022). "Dually aptamer-modified nano-systems against CD44 on CSCs and MUC1 on breast cancer cells displayed higher cellular uptake and efficacy against metastasis of breast cancer stem cells in athymic nude mice." (PMID 36559202, 2022). "As a pre-mRNA splicing inhibitor, HNRNPA1 regulates CD44 isoforms, and low levels of HNRNPA1 can significantly inhibit cell invasion and induce cell death in breast cancer." (PMID 35022405, 2022). "We observed that tumor cells in this model showed varying expression levels of luminal cell markers (cytokeratins 8/18 and 19), basal cell markers (cytokeratin 5 and SMA) and other breast cancer epithelial markers such as HER2 and CD44." (PMID 35121992, 2022). "For example, in a recent study, Li and colleagues compared the ratio of CD44+/CD24− and ALDH1+ cell populations across different breast cancer molecular subtypes and showed that MCF-7 cell line (Luminal A subtype) has the lowest ratio of both cell populations." (PMID 36482488, 2022).
breast carcinoma (continued). "Our previously published data also show that compared to adherent breast cancer cells, suspension cultures promote stemness, as shown with real-time quantitative PCR (qRT-PCR) for BMI1, NANOG and CD44." (PMID 35195687, 2022). "Apart from CD44+CD24−/low and ALDH1+, various markers have been reported to identify and isolate BCSCs in human and mouse breast cancer, which supports further research on BCSCs and provides a premise for clinical BCSC targeting." (PMID 35805056, 2022). "Cluster of differentiation 44 (CD44) is a well-known CSC marker in various cancers, as well as a key role player in metastasis and relapse of breast cancer." (PMID 36289750, 2022). "Currently, the CSC surface markers CD24, CD44, CD133 and ALDH have been widely used in breast cancer for the isolation of BCSCs." (PMID 35053617, 2022). "We discovered that the mRNA levels of various genes were upregulated in CD44 knockdown cells, and we focused on FOXA2, which has been reported to inhibit epithelial to mesenchymal transition in breast cancer." (PMID 36289750, 2022). "For breast cancer cells, IL-6/JAK/Stat3 signaling pathway is essential to maintain the CSCs property (CD44+CD24− cells), which suggested a prospective therapy mean to target the stem-like breast cancer cells." (PMID 36678534, 2022). "For instance, a sub-set of breast cancer cells with CD44+/CD24−/low have a more aggressive phenotype, resulting in drug resistance and breast cancer metastasis." (PMID 35743249, 2022). "The regulatory role of FUCA1 on two cancer stemness marker, CD44 and CD15, implies its potential function in recurrent of breast cancer." (PMID 36046653, 2022). "Calreticulin maintains the breast CSC properties of CD24-/CD44+ and ALDH+ and promotes breast cancer progression via Wnt/β-catenin signaling in an HIF-1-dependent manner." (PMID 35464064, 2022). "Recently, is has been revealed that ASCs are able to fuse spontaneously with breast cancer cells, where breast cancer stem cell (CSC) markers CD44+CD24−/lowEpCAM+ are enriched in this fused population." (PMID 36010901, 2022). "In order to scrutinize this evidence deeper and based on the result that the mesenchymal breast cancer stemness markers ZEB1 and CD44 best correlated with 3D mammosphere growth, we adopted an alternative protocol." (PMID 35348275, 2022). "While the E-cad expression level was higher, and CD-44 and C- Myc levels were lower in DMSO-treated breast cancer cells, TGF-B treatment reduced E-cad levels in both cell lines, and the reduction was insignificant in the mesenchymal-like MDA-MB-231." (PMID 36077256, 2022). "The HH signaling pathway is also activated in the CSC-enriched CD44+CD24−/low population and side population of the MCF7 breast cancer cell line." (PMID 35846378, 2022). "Since then, CSCs have been reported in other cancers: breast cancer (CSC markers: CD44, CD24, and ALDH-1), colon cancer (CSC markers: CD24, CD44, CD133, and LGR5), and melanoma (CSC markers: CD34 and ABCB5)." (PMID 35740975, 2022). "By contrast, another study indicated that a shift in CD44 expression from CD44v to the CD44s was necessary for EMT and required for breast cancer progression." (PMID 36678534, 2022). "Higher expression of the endothelial marker ANTXR1 was found on the cell surface of CD44+CD24− and ALDH1+ of the TMD231 breast cancer cell line." (PMID 35563449, 2022). "The synergistic effect of these micelles on cell cytotoxicity was tested in the MDA-MB-231 breast cancer cell and OVCAR8TR ovarian cancer cells, both overexpressing CD44." (PMID 35785191, 2022). "For example, CD36 is coexpressed with the stemness markers CD44+/CD133+/ALDH+ in breast cancer, with CD44bright in OSCC, and with CD44+/CD133+/ITGA6+ in GBM." (PMID 36568966, 2022).
breast carcinoma (continued). "At the same time, inhibition of Notch1 by specific antibodies significantly reduces the subpopulation of CSCs with the CD44+ CD24 phenotype and the frequency of brain metastases in breast cancer." (PMID 35563449, 2022). "In breast cancer, the ESA+CD44+CD24− population is considered as stem-cell-like cell (or stemness) population because it has high aggressiveness, tumorigenicity, and self-renewal capacity and is closely involved in distant metastasis." (PMID 36009455, 2022). "Oligo-HA-induced physical interaction between the primary HA receptor CD44 and TLR2, and TLR4 triggers pro-inflammatory cytokine and chemokine production in breast cancer cells." (PMID 36613567, 2022). "Our recent work demonstrated that the breast tumor-initiating cell marker CD44 is highly enriched in CTC clusters and predicts an unfavorable overall survival of patients with breast cancer, especially TNBC." (PMID 36193887, 2022). "Metformin treatment significantly reduces the sphere-forming ability and inhibits proliferation in the CD44+CD24− and ALDH+ stem-cell-rich population in breast cancer cells." (PMID 35159385, 2022). "At the same time, CD44 interacted with P300 and SIRT1 led to MDR1 and BCL-xl gene expression and chemoresistance through the β-catenin signaling pathway in breast cancer cells." (PMID 36678534, 2022). "In preclinical studies, NIR-PIT targeting CD44 and CD133, which are known as cancer stem cell markers in breast cancer and glioblastoma, has been demonstrated to inhibit tumor growth." (PMID 36297471, 2022). "As breast cancer stem cells are characterized as CD44 + /CD24 − we trypsinized the MDA-MB-231 G85 and GNS spheres, stained them with CD44 and CD24 specific antibodies, and analyzed by flow cytometry." (PMID 35879327, 2022). "When GPNMB-positive cells form spheres in breast cancer, the expression levels of CSC markers such as SOX2, NANOG, OCT4, CD44, CD133, and FOXO3 are elevated." (PMID 36061142, 2022). "RHAMM and CD44 were shown to interact in an HA-dependent autocrine system to regulate signaling via ERK1,2, resulting in increased motility of invasive breast cancer cells." (PMID 36613567, 2022). "We chose CD44+/CD24−/low and ALDH+ as the biomarker of MDA-MB-231 BCSCs compared with the common MDA-MB-231 breast cancer cells." (PMID 34123797, 2021). "The luminal breast cancer cell lines (e.g., MCF7) are reported to be enriched in the CD44−/low/CD24+ cell population." (PMID 33801148, 2021). "Here, we tested the effects of mAbs against CD44 and RHAMM on MB-231 breast cancer cell behavior in our model." (PMID 34338608, 2021). "In our study, the proportions of CD44+/CD24−/low and ALDH+ for MDA-MB-231 BCSCs were, respectively, 70.5 and 79.3%, while the proportions for common breast cancer cells were very low." (PMID 34123797, 2021). "The breast cancer stem cell markers CD47, CD44, CD24, and CD133 have all been extensively studied and reviewed." (PMID 34205080, 2021). "Positive staining was demonstrated on sections of control human tissues: tonsil for CD44, seminoma for OCT4 and NANOG, skin epidermis for SOX2, breast carcinoma for KLF4, and colon mucosa for c-MYC." (PMID 34685477, 2021). "Interaction of CD44 and its ligand, hyaluronan, activates the Src/ERK signaling pathway, leading to acquired resistance to PI3Kα inhibitor, BLY719, in luminal breast carcinomas." (PMID 34831139, 2021). "Because postoperative therapies also affect the DFS, we further analyzed the frequency of CD44-/CD24- cells in TNBC patients with chemotherapy and luminal breast cancer patients with hormone therapy." (PMID 34318746, 2021). "As presented by the expression of CD44/CD24 and tumor sphere formation in MCF-7 and MDA-MB-231, CSNK1G2 also affected the expression of breast stem cell-markers only in ER+ breast cancer cells." (PMID 33861751, 2021).